TRAJ32 (T cell receptor alpha joining 32)
Gene: T-cell receptor joining (J) gene on chromosome 14 (22,509,341 to 22,509,406, forward strand). Ensembl gene ENSG00000211857.
Diseases named in the same sentence as TRAJ32 in open-access papers:
TRAJ32 is named in the same sentence as 1 disease in open-access papers, as found by Europe PMC text mining. Sharing a sentence is not in itself a finding about the gene and the disease. The quoted sentences say what the papers report.
cancer (1 paper, 2025). A tumor composed of atypical neoplastic, often pleomorphic cells that invade other tissues. "Of the remaining cancer-activated MR1-restricted TCRs, some used the MAIT cell–preferred TRAJ20 and TRAJ12 to generate a similarly placed tyrosine and others used TRAJ26, TRAJ47, or TRAJ32 to encode this tyrosine residue." (PMID 39744940, 2025).